BHLHE40 (basic helix-loop-helix family member e40)
Diseases named in the same sentence as BHLHE40 in open-access papers (continued):
Sharing a sentence is not in itself a finding about the gene and the disease.
Miscarriage (1 paper, 2025). A pregnancy that ends at a stage in which the fetus is incapable of surviving on its own, defined as the spontaneous loss of a fetus before the 22th week of pregnancy. "BHLHE40 expression is increased during STB differentiation but reduced in villous samples from women with miscarriages." (PMID 40911186, 2025). "In BHLHE40‐KO STBs, secretion of estrogen, progesterone, and HCG was reduced, mirroring the hormonal deficiency in miscarriage patients." (PMID 40911186, 2025). "BHLHE40 expression was increased during STB differentiation but reduced in villous from patients with miscarriages." (PMID 40911186, 2025). "Furthermore, pathological BHLHE40 reduction may underlie placental deficiencies due to STB dysfunction, providing mechanistic insights for therapeutic strategies of pregnancy complications such as miscarriage." (PMID 40911186, 2025). "Considering our findings of reduced BHLHE40 levels in first‐trimester villous samples from women with miscarriages, the decline in HCG levels in these patients might be, at least in part, due to low levels of BHLHE40." (PMID 40911186, 2025).
myocardial inflammation (1 paper, 2024). "Previous studies showed that Bhlhe40 is involved in the development of inflammatory diseases such as periodontal inflammation, myocardial inflammation, and rheumatoid arthritis." (PMID 38402153, 2024).
Obesity (1 paper, 2024). Accumulation of substantial excess body fat. "Our study identified three key circadian genes (BHLHE40, PPP1CB, and CSNK1E) associated with obesity." (PMID 39351493, 2024). "However, research on the implications of BHLHE40 in the pathogenesis of obesity is relatively limited, with most studies focusing on the immune response." (PMID 39351493, 2024). "Furthermore, the negative regulation of circadian genes by BHLHE40 gradually leads to circadian disruption in central and peripheral organs, potentially affecting lifestyle choices and exacerbating obesity." (PMID 39351493, 2024). "These animal experiments differ from our study results, suggesting that other molecular changes regulated by BHLHE40 may contribute to the development of obesity." (PMID 39351493, 2024). "Moreover, our research showed that BHLHE40 amplifies the inflammatory response in the pathogenesis of obesity by instigating the adaptive immune response of Treg cells and CD4+ T cells and promoting the chemotaxis of vital immune molecules, such as CCR, CXCL, and TNFRSF, in tissues." (PMID 39351493, 2024). "Our research findings suggest that the circadian genes (BHLHE40, CSNK1E, and PPP1CB) could serve as novel biomarkers for understanding the pathogenesis of obesity." (PMID 39351493, 2024). "In conclusion, the key circadian genes (BHLHE40, CSNK1E, and PPP1CB) may serve as novel biomarkers for understanding obesity pathogenesis and have significant correlations with infiltrating immune cells, thus providing potential new targets for obese prevention and treatment." (PMID 39351493, 2024).
osteoarthritis (1 paper, 2021). A noninflammatory degenerative joint disease occurring chiefly in older persons, characterized by degeneration of the articular cartilage, hypertrophy of bone at the margins and changes in the synovial membrane. "Deletion of Bhlhe40 in mice results in increased BMC and density, but a role in osteoarthritis pathogenesis has not been postulated and BHLHE40 has not been associated with osteoarthritis in GWAS." (PMID 33473114, 2021).
Osteopenia (1 paper, 2021). Osteopenia is a term to define bone density that is not normal but also not as low as osteoporosis. "According to the newest reports, BHLHE40 deficiency resulted in accelerated osteopenia through attenuated PI3KCA/Akt/GSK3β signaling." (PMID 34917665, 2021).
osteoporosis (1 paper, 2022). A condition of reduced bone mass, with decreased cortical thickness and a decrease in the number and size of the trabeculae of cancellous bone (but normal chemical composition), resulting in increased fracture incidence. "Our research reveals a novel Bhlhe40/c-Fos/Nfatc1 axis involved in regulating osteoclastogenesis and shows that osteoporosis caused by estrogen deficiency and aging can be rescued by regulating Bhlhe40 in mice." (PMID 35619122, 2022). "Our research showed that osteoporosis caused by estrogen deficiency and aging can be rescued by regulating Bhlhe40." (PMID 35619122, 2022). "We showed that Bhlhe40 upregulation is tightly associated with osteoclast differentiation and osteoporosis." (PMID 35619122, 2022). "In senile osteoporosis, which is caused by multiple factors, the inhibition of Bhlhe40 should be combined with other treatments." (PMID 35619122, 2022). "In this study, we found that Bhlhe40 was upregulated during osteoclastogenesis and was associated with osteoporosis." (PMID 35619122, 2022). "Finally, we established a mouse model of estrogen-deficient and senile osteoporosis and found a significant improvement in abnormal bone resorption in Bhlhe40-deficient mice, suggesting that Bhlhe40 is an effective target for the treatment of osteoporosis." (PMID 35619122, 2022). "Moreover, Bhlhe40 deficient mice resisted estrogen deficiency and aging-induced osteoporosis." (PMID 35619122, 2022). "In addition, senile Bhlhe40−/− mice showed similar bone mass as adult Wt mice, which demonstrated the possibility of using Bhlhe40 as a treatment target for aging-induced osteoporosis." (PMID 35619122, 2022). "Therefore, Bhlhe40 may be a promising target for the treatment of osteoporosis." (PMID 35619122, 2022). "Moreover, we labeled BMMs or OCs with CD11b or CTSK and found Bhlhe40 upregulation in BMMs and OCs from ovariectomized (OVX)-induced osteoporosis mice compared to those from sham-operated control mice." (PMID 35619122, 2022).
osteosclerosis (1 paper, 2022). Abnormally high bone density. "In addition, bone marrow transplantation showed that osteoclasts were the culprit of osteosclerosis caused by Bhlhe40 deficiency." (PMID 35619122, 2022). "Osteosclerosis in Bhlhe40−/− mice was dominated by osteoclasts instead of the microenvironment." (PMID 35619122, 2022).
pancreatic ductal adenocarcinoma (1 paper, 2023). An infiltrating adenocarcinoma that arises from the epithelial cells of the pancreas. "Interestingly, BHLHE40 can drive pro-tumor neutrophils with hyperactivated glycolysis in pancreatic ductal adenocarcinoma." (PMID 36626244, 2023). "ARNTL2, BHLHE40 are reported to promote pancreatic ductal adenocarcinoma progression." (PMID 36626244, 2023).
periodontitis (1 paper, 2022). An acute or chronic inflammatory process that affects the tissues that surround and support the teeth. "Bhlhe40 deficiency inhibits inflammation in periodontitis, obesity and hypertension." (PMID 35619122, 2022). "In contrast, the lack of Bhlhe40 reduces cement loss caused by Porphyromonas gingivalis in a periodontitis model." (PMID 35619122, 2022).
placental insufficiency (1 paper, 2025). Failure of the placenta to deliver an adequate supply of nutrients and oxygen to the fetus. "Therefore, BHLHE40 deficiency in STBs may contribute to placental insufficiency, potentially leading to adverse pregnancy outcomes." (PMID 40911186, 2025).
psoriasis (1 paper, 2020). An autoimmune condition characterized by red, well-delineated plaques with silvery scales that are usually on the extensor surfaces and scalp. "We found that rs3132089, a promoter variant of the HCP5 gene, is highly linked with psoriasis risk SNP rs3134792 (r2 = 0.9253) and located on the binding motif of ARNT and BHLHE40 proteins, which is predicted to result in decreased binding." (PMID 31969149, 2020).
T-cell lymphoma (1 paper, 2020). "Moreover, analysis of expression profiling data from selected ALCL (GSE19069) and peripheral T-cell lymphoma patients (GSE6338) showed correlated activities of HHEX, CASP8, FOXO3 and BHLHE40, supporting this regulatory connection." (PMID 32922661, 2020).
triple-negative breast carcinoma (1 paper, 2018). An invasive breast carcinoma which is negative for expression of estrogen receptor (ER), progesterone receptor (PR), and human epidermal growth factor receptor 2 (HER2). "We found that high expression of BHLHE40 or HBEGF is significantly associated with shorter interval of relapse-free survival (RFS) among patients diagnosed with triple-negative breast cancer (TNBC; n = 255) and patients treated with chemotherapy (n = 602)." (PMID 30285805, 2018). "Public databases provided evidence linking high expression of BHLHE40 and HBEGF to poor prognosis of triple-negative breast cancer." (PMID 30285805, 2018).
uterine tumors (1 paper, 2020). "Multiple deletion mutations in the mesoderm group (e.g., Deletion-3 prime UTR ADAR, BHLHE40, ZFX, etc.)mainly occur in the cases with uterine tumors." (PMID 33308219, 2020).
tumor (67 papers, 2004 to 2026). "Using animal and human models of MMRd, we determined that interactions between MHC+ C1Q+ CXCL9+ macrophages and TCF+ BHLHE40+ PRF1+ T cell subsets are associated with control of MMRd tumor growth, during anti-PD-1 treatment." (PMID 40027748, 2025). "We show here that BHLHE40 is downregulated in PCa tumor samples and low expression is linked to lower survival of PCa patients." (PMID 38902772, 2024). "EMT is closely associated with tumor invasion and metastasis, and in the current study, BHLHE40 overexpression promoted cell migration and invasion." (PMID 37377917, 2023). "Through comprehensive analysis of RNA sequencing and public databases, we identified BHLHE40 as a valuable biomarker associated with CAFs, immune cell infiltration, and tumor cell stemness in PDAC." (PMID 37377917, 2023). "Accordingly, loss of BHLHE40 in T cells abrogated the anti-tumor effects of immune checkpoint inhibitors." (PMID 35454831, 2022). "Taken together, these studies demonstrate that in all subtypes of brain carcinoma, tumor aggression is associated with an increase in the expression of BHLHE40." (PMID 32577154, 2020). "BHLHE40 encoding DEC1 mediates cellular senescence by its direct target gene CCNG2, that encodes the atypical and tumor suppressive Cyclin G2, as a novel tumor suppressive axis encompassing androgen receptor-BHLHE40-Cyclin G2 in order to mediate cellular senescence in PCa cells." (PMID 38902772, 2024). "The authors also found that Bhlhe40-dependent metabolic fitness is strongly associated with a functional epigenetic state required for the development and polyfunctionality of tissue resident and tumor infiltrating lymphocytes." (PMID 34199142, 2021). "However, the frequency of nuclear BHLHE40 was higher in well differentiated, than in moderately, or poorly differentiated HCC, arguing that loss of BHLHE40 is associated with tumor progression." (PMID 32577154, 2020). "Thus, HCC truly represents the dichotomy of BHLHE40 – both as tumor promoter during initiation, but with loss of function in further progression." (PMID 32577154, 2020). "Similarly, in primary tumours these genes showed significant downregulation (3–4-fold), together with other genes associated with light perception and phototransduction, such as Cngb1, Nrl (6-fold) or Bhlhe40." (PMID 32581213, 2020). "CONCLUSION: CAF-exo circ_0067557 promotes EMT, invasion, metastasis, and tumor progression in CRC by recruiting BHLHE40 and activating OTUB2 transcription." (PMID 42115880, 2026). "In vivo experiments further confirmed that circ_0067557 markedly enhanced tumor growth and distant metastasis through the BHLHE40/OTUB2 signaling axis." (PMID 42115880, 2026). "Particularly, we reported new subtypes of tumor-associated CD8+ T cells characterized by different TBX21 and BHLHE40 activity, both of which are known regulators of CD8+ T cell functionality." (PMID 39907554, 2025). "Recent work further implicates BHLHE40-driven glycolytic reprogramming in polarizing neutrophils toward a pro-tumor phenotype, highlighting metabolic targeting as a therapeutic strategy." (PMID 40777001, 2025). "Collectively, these data propose that BHLHE40 is upregulated by SAL in 2D, 3D spheroids, ex vivo and in vivo, and that BHLHE40 mediates androgen-induced cellular senescence, which serves as a tumor suppressor pathway in PCa." (PMID 38902772, 2024). "Phosphodiesterase 4B (PDE4B) was reported as regulated by BHLHE40 which was a direct regulator of the pro-tumor gene and played a key role in the polarization of neutrophils in PDAC18." (PMID 38769374, 2024). "BHLHE40 has been reported to have tumor suppressive functions and has been shown to affect energy metabolism by regulating PGC-1α, SREBP-1c, PKLR, PCK2, FASN, and PPARγ." (PMID 38301894, 2024).
tumor (continued). "This suggests that either BHLHE40 has independently of regulating circadian rhythm a tumor suppressive function or alternatively, that a proper circadian rhythm is part of a tumor suppressive program in cancer." (PMID 38902772, 2024). "In tumor immunity, BHLHE40 also promotes the commitment of tumor-infiltrating lymphocytes (TILs), which resemble Trm cells." (PMID 38301894, 2024). "Further, RNA-seq and ChIP-seq analysis indicate that the atypical tumor suppressive cyclin G2 emerged as a novel downstream target of BHLHE40 and a mediator of SAL-induced cellular senescence." (PMID 38902772, 2024). "The IHC staining of PCa clinical samples showed that BHLHE40 was expressed at a higher level in tumor samples than in para‐tumor tissues." (PMID 38064101, 2024). "In nAg.Bhlhe40HiCd8, the top defining marker of this cluster was Bhlhe40, which we previously demonstrated was upregulated in tumor-specific T cells and required for CD4 and/or CD8 T cell effector function and response to ICT21." (PMID 38187708, 2024). "One tumor suppressive pathway by BHLHE40 identified here is the regulation of cellular senescence and evidence of other types of dormancy." (PMID 38902772, 2024). "Because BHLHE40 is necessary for TILs to play a critical role in the immune system to suppress tumor growth, BHLHE40 acts as a tumor suppressor not only by functioning in tumor cells themselves but also by activating anti-tumor immune functions in the host." (PMID 38301894, 2024). "Integrated transcriptome and epigenetic multiomics analyses of the paired PCa organoids indicate that the basic helix‐loop‐helix transcription factor 40 (BHLHE40) is significantly upregulated in tumor samples." (PMID 38064101, 2024). "BHLHE40 mRNA is significantly diminished in PCa samples compared to adjacent tumor tissues supporting the notion that BHLHE40 has tumor suppressor function." (PMID 38902772, 2024). "Of these, TAN-0 and TAN-1 exhibited high expression of BHLHE40, indicating their role as tumor-promoting TANs." (PMID 39261943, 2024). "Here, integrated transcriptome and epigenetic multi‐omics analyses of paired (tumor and para‐tumor tissues) PCa organoids indicated that BHLHE40 was upregulated in PCa." (PMID 38064101, 2024). "On the other hand, ATF3, BHLHE40, ZNF263, and FOXP2 transcription factors were strongly associated with GADD45B-low tumor cells." (PMID 37608794, 2023). "In vitro experiments demonstrated that overexpression of BHLHE40 promoted tumor cell invasion and stemness while inhibiting anti-tumor immunity by inducing apoptosis of CD8+ T cells." (PMID 37377917, 2023). "In single-cell sequencing analysis, ITGA2, ITGA3, ADAM9, and BHLHE40 were all highly expressed in malignant ductal cells, suggesting important roles in tumor progression." (PMID 37377917, 2023). "BHLHE40 is also an important immune regulatory factor that can inhibit anti-tumor immunity by affecting the levels of cytokines secreted by T cells." (PMID 37377917, 2023). "BHLHE40, a critical transcription factor for remodeling of the tumor immune microenvironment, has been described to be substantially increased in a variety of tumor-associated immune cells." (PMID 37773521, 2023). "The BHLHE40 gene was also considerably more expressed in normal and tumor samples than any other core clock gene." (PMID 36895015, 2023). "Overexpression of BHLHE40 caused the differentiation of tumor-associated neutrophils into a protumor subpopulation (TAN-1) and enhanced tumor immune suppression." (PMID 37588985, 2023). "BHLHE40 expression is also inhibited by local PD-1 signaling and is important for tumor-infiltrating lymphocytes (TILs) reactivation after anti-PD-L1 inhibition." (PMID 35806162, 2022). "While we focused on the role in RPE development, it has been known that BHLHE40 is involved in circadian rhythm and tumor progression." (PMID 36412639, 2022).